ZNF217 (zinc finger protein 217)
Diseases named in the same sentence as ZNF217 in open-access papers (continued):
Sharing a sentence is not in itself a finding about the gene and the disease.
breast carcinoma (continued). "In breast cancer, higher ECM stiffness supports oncogene expression, including zinc finger protein 217 (ZNF217), and activates the protein kinase B (AKT) signaling pathway, leading to enhanced cell proliferation." (PMID 40686923, 2025). "The same authors observed that hypoxia also leads to the overexpression of Nanog and another pluripotency factor, KLF4, in a ZNF217-dependent and HIF-dependent manner in breast cancer cells." (PMID 37369946, 2023). "We also found that our deep-learning classifier predicted well (AUC > 0.65) on the CNA status in breast cancer, including six genes of FGFR1, EIF4EBP1, KAT6A, HEY1, ZNF217, and RAB25." (PMID 34556802, 2021). "This study suggests that m6A demethylase ALKBH5 and m6A methyltransferase inhibitor ZNF217 have important effects on BCSC phenotype and breast cancer metastasis." (PMID 34745269, 2021). "ZNF217 increases pluripotency factor KLF4 and NANOG expression in an m6A-dependent manner, promoting pluripotency factor expression and breast cancer stem cell (BCSC) specification." (PMID 33162550, 2020). "ZNF217, an m6A methyltransferase inhibitor targeting METTL3, is upregulated in hypoxia-induced breast cancer cells." (PMID 33162550, 2020). "Till now, a few of studies have shown aberrant expression of five m6A regulators in breast cancer and clarified the molecular mechanism of ALKBH5- and ZNF217-mediated tumor occurrence." (PMID 33585234, 2020). "One of these fusions, SULF2--ZNF217 predicted by nine different methods in cell line MCF7, was recently predicted to be a potential driver of breast cancer." (PMID 31639029, 2019). "In breast cancer, LncRNA ATB regulates ZEB1 and ZNF-217, inducing epithelial mesenchymal transition, which leads to trastuzumab resistance and increased invasion and metastasis." (PMID 29599647, 2018). "Co-amplifications of other driver loci in breast cancer are observed, for example chr20:ZNF217 and chr8:MYC is seen in 18 samples (P = 1e−04) and chr20:ZNF217 and chr8:ZNF703 in 11 samples (P = 9e−03) (available at Annals of Oncology online)." (PMID 30252041, 2018). "Our findings differ from previous reports that have shown total RNA m6A levels in breast cancer cell lines decrease in hypoxia conditions through HIF mediated induction of the demethylase ALKBH5 and/or METTL3 sequestration by ZNF217." (PMID 30131850, 2018). "What's more, miR-200c restored trastuzumab sensitivity in trastuzumab-resistant cells and suppressed invasion of breast cancer cells by silencing of ZEB1, ZNF217 or blockade of TGF-β signaling." (PMID 27036021, 2016). "Although hypoxia induced the BCSC phenotype in all breast-cancer cell lines analyzed, it did so through variable induction of pluripotency factors and ALKBH5 or ZNF217." (PMID 27590511, 2016). "ZNF217 induced overexpression of both the Bcl-XL and Aurora-A proteins in paclitaxel-resistant ZNF217-overexpressing breast cancer cells, and expression of BCL2L1 protein correlated with that of ZNF217 mRNA in colorectal tumors." (PMID 26431164, 2015). "It has been confirmed down-regulation of miR-200c promote invasiveness and EMT of breast cancer by regulating the expression of ZEB1 and ZNF217." (PMID 25871474, 2015). "In particular, miR-200c, which targets both ZNF217 and ZEB1, re-sensitized trastuzumab-resistant breast cancer cells to trastuzumab in vitro and suppressed metastases in vivo." (PMID 26431164, 2015). "More importantly, nested feedback circuits of miR-200c/ZEB1 and miR-200c/ZNF217/TGF-β/ZEB1 contribute to EMT correlated with trastuzumab resistance and metastasis of breast cancers." (PMID 25871474, 2015).
breast carcinoma (continued). "Future investigations will explore the connection between ZNF217 expression levels in breast tumors with clinical outcome and, importantly, whether ZNF217 plays a transcriptional role in aberrant ERα signaling, contributing to breast cancer and therapy resistance." (PMID 24962896, 2014). "Here, we present a large-scale functional genomic analysis of ZNF217, which provides insights into the regulatory role of ZNF217 in MCF7 breast cancer cells." (PMID 24962896, 2014). "To gain further insight into the regulation of gene expression by ZNF217, we employed an RNA-seq approach following ZNF217 silencing to characterize the direct and indirect targets of ZNF217 in MCF7 breast cancer cells." (PMID 24962896, 2014). "This work supports further exploration into the connection between ZNF217 expression levels in breast tumors with clinical outcome and, importantly, whether ZNF217 plays a transcriptional role in aberrant ERα signaling, contributing to breast cancer and therapy resistance." (PMID 24962896, 2014). "In breast cancer, multiple genes localized to 20q have been identified as oncogenes, including Aurora-A kinase (AURKA), ZNF217, UBE2C and TPX2." (PMID 24344117, 2013). "We found that ZNF217 confers a highly proliferative and paclitaxel-resistant phenotype to MDA-MB-231 breast cancer cells." (PMID 21059223, 2010). "This subset included known breast cancer genes, like EGFR (7p11), FGFR1 (8p12), ERBB2 (17q12), PPM1D (17q23) and ZNF217 (20q13)." (PMID 19582160, 2009). "For instance, ZNF217 was reported to reduce mRNA m6A methylation in embryonic stem cells and breast cancer cells by sequestering the m6A 'writer' METTL3, thereby supporting embryonic stem cell pluripotency and promoting breast cancer progression 40-43." (PMID 40093906, 2025). "Unfortunately, most studies on ZNF217 have been performed in ovarian and breast cancer, and none have yet been performed in cholangiocarcinoma." (PMID 36646721, 2023). "In addition, the inhibition of ZNF217-dependent m6A methylation of NANOG and KLF4 mRNA was found to be enhanced in breast cancer cells under hypoxia, thus promoting the occurrence and development of breast cancer." (PMID 35251177, 2022). "Previous reports using breast cancer stem cells have shown that hypoxic activation of HIF led to decreased RNA methylation through HIF-mediated induction of the demethylase ALKBH5 and METTL3 suppressor ZNF217." (PMID 30131850, 2018). "For example, lnc-ATB could upregulate ZEB1 and ZNF-217, and then induce EMT, leading to trastuzumab resistance and invasion-metastasis in breast cancer." (PMID 28086241, 2017). "However, in every breast cancer line, the hypoxic induction of pluripotency factor and ALKBH5 or ZNF217 expression was HIF-dependent." (PMID 27590511, 2016). "Another predicted target, ZNF217, has not been reported as a miR-503 target but was recently identified as both a biomarker and an oncogene in breast cancer." (PMID 27539783, 2016). "Irrespective of cancer types, abnormal ZNF217 immunoreactivity was an indicator of worse 3-year (Breast cancer: P = 0.005) (Others types: P = 0.02) and 5-year prognosis respectively (Breast cancer: P = 0.01) (Others types: P = 0.0004)." (PMID 27007163, 2016). "ZNF217 expression levels thus allow the re-stratification of breast cancer patients considered as having a good prognosis, for whom no other widely used biomarker is currently available." (PMID 26431164, 2015). "We found lnc-ATB could promote trastuzumab resistance and invasion-metastasis cascade in breast cancer by competitively biding miR-200c, up-regulating ZEB1 and ZNF-217, and then inducing EMT." (PMID 25871474, 2015). "We found that lnc-ATB could promote trastuzumab resistance and invasion-metastasis cascade in breast cancer by competitively biding miR-200c, up-regulating ZEB1 and ZNF-217, and then inducing EMT." (PMID 25871474, 2015).
breast carcinoma (continued). "In the current study, we reported that lnc-ATB, which had been reported to be activated by TGF-β, promote trastuzumab resistance and invasion-metastasis cascade in breast cancer by competitively biding miR-200c, up-regulating ZEB1 and ZNF-217, and then inducing EMT." (PMID 25871474, 2015). "Additionally, lnc-ATB significantly correlated with the expression of ZNF217 and ZEB1 in the tissues of TR breast cancer patients (P = 0.025 and P < 0.001 respectively)." (PMID 25871474, 2015). "Therefore, nested feedback circuits of lnc-ATB/miR-200c/ZEB1 and lnc-ATB/miR-200c/ZNF217/TGF-β/ZEB1 contribute to EMT correlated with trastuzumab resistance and metastasis of breast cancer." (PMID 25871474, 2015). "Recent studies have highlighted ZNF217's role in modulating m6A RNA methylation, showcasing its diverse mechanisms of action, from blocking the m6A "writer" METTL3 in embryonic stem cells and breast cancer cells to enhancing the transcription of the m6A "eraser" FTO in adipocytes 40-45." (PMID 40093906, 2025). "The importance of ZNF217 for TBX2-CoREST repression may also explain why disruption of ZNF217 interactions within the complex by SP-2509 was effective in de-repressing TSGs and inhibiting breast cancer cell proliferation." (PMID 35687133, 2022). "However, it would also be informative to investigate the role of ZNF217 in our HMEC-based system to see if it interacts with METTL3 and the m6A system and whether that interaction is regulated during breast cancer progression." (PMID 30131850, 2018). "ZNF217, a notable member of this class of genes, is a Krüppel-like finger (KLF) protein that acts as a transcriptional regulator that amplifies the estrogen response in breast cancer and has been identified as a biomarker of poor survival in patients with Luminal A (ER+) breast tumors." (PMID 27539783, 2016). "In terms of predicting treatment response, retrospective analysis of two independent expression datasets from breast cancer patients who received neoadjuvant chemotherapy, showed lower levels of ZNF217 mRNA in responders compared to in non-responders (p = 0.04 and p < 0.0001)." (PMID 26431164, 2015). "A model can be proposed whereby ZNF217 cooperates with Aurora-A, BCL2L1 or eEF1A2 in neoplastic progression of breast cancer through genomic co-amplification and/or through ZNF217-driven molecular regulation, which might amplify the impact of any genomic amplification." (PMID 26431164, 2015). "Furthermore, ZNF217, an m6A methyl-transferase inhibitor, inhibits the m6A modification of several pluripotency factor mRNAs, including NANOG, KLF4 and SOX2 in breast cancer to promote the CSC-like phenotype and breast cancer metastasis under hypoxic conditions." (PMID 34831207, 2021). "Although all seven breast cancer cell lines displayed BCSC enrichment and increased expression of one or more pluripotency factors in response to hypoxia, neither ALKBH5 nor ZNF217 expression was induced by hypoxia in SUM149 or T47D cells." (PMID 27590511, 2016).
breast tumors (14 papers, 2010 to 2026). "Patients with high ZNF217 mRNA expression levels in primary breast tumors had a higher risk of developing BM." (PMID 36551531, 2022). "ZNF217 xenografts in mice were prone to developing spontaneous metastases, especially in lung, liver and lymph nodes and high ZNF217 expression levels were associated with metastases in human breast tumors." (PMID 26431164, 2015). "In contrast to GATA3 and FOXA1, the ZNF217 gene is amplified at 20q13 in ~20% of breast tumors and is associated with aggressive breast disease." (PMID 24962896, 2014). "DNA methylation status at the ZNF217 locus was lower in estrogen receptor α-positive (ER+) when compared with ER-negative (ER-) breast tumors, while ER+ and ER- breast tumors display, respectively, high and low ZNF217 mRNA levels." (PMID 36551531, 2022). "First, both the RNA-seq and RT-qPCR investigations, conducted on independent primary breast tumor cohorts, identified a positive correlation between ZNF217-ΔE4 and ZNF217-WT mRNA levels." (PMID 34277402, 2021). "Using a primer pair targeting exon 3, we have previously demonstrated that the ZNF217 mRNA expression level of a breast tumor is informative and provides a powerful biomarker of poor prognosis, in particular in the Luminal subclass." (PMID 34277402, 2021). "By performing in silico RNAseq and real-time quantitative polymerase chain reaction (RT-qPCR) investigations, our study highlights the existence of ZNF217-ΔE4 transcripts in primary breast tumors." (PMID 34277402, 2021). "Using in silico RNA-seq and RT-qPCR analyses, we demonstrated for the first time the existence of ZNF217-ΔE4 transcripts in primary breast tumors, and a positive correlation between ZNF217-ΔE4 mRNA levels and those of the wild-type oncogene (ZNF217-WT)." (PMID 34277402, 2021). "The distribution of ZNF217-WT (E3-E4) and ZNF217-ΔE4 (E3-E5) mRNA levels in the primary breast tumors highlighted that the ZNF217-ΔE4 isoform mRNA expression levels are globally weaker than those of the ZNF217-WT isoform." (PMID 34277402, 2021). "We performed RT-qPCR analyses to explore ZNF217-WT (E3-E4) and ZNF217-ΔE4 (E3-E5) mRNA expression levels in a cohort of 107 human primary breast tumor samples." (PMID 34277402, 2021). "Identification of reads mapped to the exon 3 to exon 4 junction (E3-E4) of the ZNF217 gene corresponds to the expression of ZNF217-WT isoform in breast tumor samples." (PMID 34277402, 2021). "Our study has implications for personalized therapies for patients with breast tumors that overexpress ZNF217." (PMID 29312549, 2017). "ER+ breast tumors or cancer cell lines displayed higher ZNF217 expression levels compared to their ER- counterparts (p = 0.0004, p = 0.005 and p = 1 × 10−7; p = 0.009 and p = 0.0001)." (PMID 26431164, 2015). "In the original work depicting the ZNF217 gene, higher ZNF217 transcript levels were found in breast tumor samples than in the corresponding normal epithelium." (PMID 26431164, 2015). "Data-mining of microarray expression data from primary breast tumors and the corresponding clinical data showed high ZNF217 expression correlates with shorter overall survival and relapse-free survival." (PMID 24962896, 2014). "The ZNF217 gene, encoding a C2H2 zinc finger protein, is located at 20q13 and found amplified and overexpressed in greater than 20% of breast tumors." (PMID 24962896, 2014). "ERalpha expression highly correlates with ZNF217 in lysates from breast tumors (n = 15), and ERalpha co-precipitates ZNF217 and its binding partner CtBP2 from nuclear extracts." (PMID 24962896, 2014). "Here, we demonstrate a previously unknown mechanism of TBX2-mediated gene repression in breast tumours, whereby TBX2 physically interacts with CoREST-associated proteins LSD1, HDAC1 and the ZNF217 oncogene." (PMID 35687133, 2022). "RNA-seq files obtained from the TCGA repository were used to decipher whether the ZNF217-ΔE4 isoform is expressed in 1,097 primary breast tumors." (PMID 34277402, 2021).
breast tumors (continued). "In conclusion, the prognostic value of ZNF217 appears most powerful in the breast tumor subtypes where ERα expression and ERα signaling are more prominent, which may reflect the impact of ZNF217 in modulating existing active ERα signaling." (PMID 26431164, 2015). "We also looked for a correlation between ZNF217 and ERα protein expression in breast tumor samples." (PMID 24962896, 2014). "However, at the time when those studies were conducted, the possible expression of the ZNF217-ΔE4 isoform in breast tumors was unknown." (PMID 34277402, 2021). "The high overlap between differentially regulated genes co-bound by ZNF217 and ERα and the poor prognosis of patients with breast tumors that overexpress ZNF217 suggested that ZNF217 may have a regulatory role in expression changes that occur in tamoxifen-resistant breast tumors." (PMID 24962896, 2014). "Zinc-finger protein 217 (ZNF217) which function as part of a transcriptional repressor complex regularly increases in cancers; “breast tumor and colorectal cancer” and upregulated ZNF217 is typically linked with poor prognosis." (PMID 33833800, 2021). "PTK6 maps to a chromosomal region (20q13.3) that is frequently amplified in breast tumors and amplicons spanning this region variably contain other suspected oncogenes, such as TDE1, NCoA3, BCAS4, and ZNF217." (PMID 20668531, 2010). "Together these results inferred that the interaction and coordinated activity between TBX2 and CoREST proteins LSD1, ZNF217 and HDAC1 may be essential for repression of TSGs to promote breast tumour survival." (PMID 35687133, 2022). "Overall, the ZNF217-ΔE4 (E3-E5) mRNA levels were 6-8 fold weaker than those of ZNF217-WT (E3-E4) within a particular primary breast tumor (data not shown)." (PMID 34277402, 2021). "Further investigations revealed that estrogen signaling disruption, such as siRNA targeting ERα, could trigger epigenetic silencing (hypermethylation) of the ZNF217 gene and that the methylation status at the ZNF217 locus was higher in ERα-negative (ER-) versus ER+ breast tumors." (PMID 26431164, 2015).